DPP9 (dipeptidyl peptidase 9)
Description:
Dipeptidyl peptidase that cleaves off N-terminal dipeptides from proteins having a Pro or Ala residue at position 2. Acts as a key inhibitor of caspase-1-dependent monocyte and macrophage pyroptosis in resting cells by preventing activation of NLRP1 and CARD8. Sequesters the cleaved C-terminal part of NLRP1 and CARD8, which respectively constitute the active part of the NLRP1 and CARD8 inflammasomes, in a ternary complex, thereby preventing their oligomerization and activation. The dipeptidyl peptidase activity is required to suppress NLRP1 and CARD8; however, neither NLRP1 nor CARD8 are bona fide substrates of DPP9, suggesting the existence of substrate(s) required for NLRP1 and CARD8 inhibition.
Synonyms: DP9; DPRP-2; DPP IX; DPLP9; DPRP2; HATIS; IMD111
Tractability: Small molecule: a structure with a bound ligand is known; a high-quality ligand is known; it belongs to a druggable protein family. PROTAC: ubiquitination databases record sites on it; its protein half-life has been measured; a small molecule that binds it is known.
Target class: Enzyme; Serine protease SC clan; Protease; Serine protease S9B subfamily; Serine protease
Chemical probes: cpd 1 (high quality)
Gene: Protein-coding gene on chromosome 19 (4,674,341 to 4,724,673, reverse strand). Ensembl gene ENSG00000142002.
Subcellular location: Cytoplasm, cytosol (Isoform 1); Nucleus (Isoform 2)
Subcellular location (Human Protein Atlas): Cytosol
Gene Ontology:
Molecular function: dipeptidyl-peptidase activity; identical protein binding; protein binding; serine-type peptidase activity
Biological process: negative regulation of programmed cell death; pyroptotic inflammatory response; proteolysis
Cellular component: cell leading edge; cytosol; microtubule; nucleus
Genetic constraint (gnomAD): Loss-of-function variants: 52 observed, 101.32 expected, observed/expected ratio (o/e) 0.51, 90% interval 0.41 to 0.65. The upper end of that interval is the gene's LOEUF score, 0.65, which puts it in group 2 of 6, group 1 being the genes least tolerant of losing a copy. Missense variants: 1,022 observed, 1,156.1 expected, observed/expected ratio (o/e) 0.88, 90% interval 0.84 to 0.93. Synonymous variants: 561 observed, 499.61 expected, observed/expected ratio (o/e) 1.12, 90% interval 1.05 to 1.2.
Homologues: Orthologues: chimpanzee DPP9 (99% identical), pig DPP9 (95% identical), macaque DPP9 (94% identical), dog DPP9 (94% identical), guinea pig DPP9 (90% identical), rat Dpp9 (89% identical), mouse Dpp9 (89% identical), zebrafish dpp9 (77% identical), tropical clawed frog dpp9 (68% identical), Drosophila melanogaster CG3744 (41% identical), Caenorhabditis elegans dpf-3 (30% identical). Paralogues in human: DPP8 (58% identical), DPP10 (21% identical), DPP6 (21% identical), DPP4 (20% identical), FAP (19% identical), APEH (12% identical).
Diseases named in the same sentence as DPP9 in open-access papers:
DPP9 is named in the same sentence as 73 diseases in open-access papers, as found by Europe PMC text mining. Sharing a sentence is not in itself a finding about the gene and the disease. The quoted sentences say what the papers report.
COVID-19 (45 papers, 2021 to 2026). A disease caused by infection with severe acute respiratory syndrome coronavirus 2. "Studies implicated the DPP9 gene was involved in Coronavirus disease 2019 (COVID-19) caused by severe acute respiratory syndrome coronavirus 2 (SARS-CoV-2)." (PMID 36172198, 2022). "As an example, we report an unannotated, alternative transcript of the inflammasome regulator DPP9 that is lung epithelium-specific, that harbours a common genetic variant associated with severe COVID-19 and lung fibrosis." (PMID 42303611, 2026). "Intriguingly, genome-wide association studies (GWAS) have revealed that two single-nucleotide polymorphisms (SNPs) (rs12610495 & rs2109069) in the DPP9 gene are associated with severe COVID-19 and greater hospitalisation rates." (PMID 40293537, 2025). "Haplotype frequency analysis revealed that the coexistence of CCL2 rs1024611-G, OAS1 rs10774671-A, and DPP9 rs10406145-G alleles in the same individual increased the presence of the severe COVID-19 phenotype (OR=2.273, 95% CI: 1.271-4.068, P=0.005305)." (PMID 38694517, 2024). "Two intronic polymorphisms in the DPP9 gene have been associated with the severe form of COVID-19 and worse clinical outcome in infected individuals." (PMID 38694517, 2024). "The real association between the CCL2, OAS1, and DPP9 variants and the presence of the severe COVID-19 phenotype was examined using multivariable logistic regression analysis to control the influence of age, sex, obesity, and comorbidities." (PMID 38694517, 2024). "The DPP9 gene, has also been found to be associated with diabetes mellitus, as well as the severity of COVID-19, thus justifying the increased disease severity in COVID-19 patients comorbid with diabetes." (PMID 39170247, 2024). "Several genetic loci, such as the TYK2 and DPP9 genes, have been identified that affect COVID-19 susceptibility and severity." (PMID 39170247, 2024). "In summary, we used context-specific eQTL datasets of fibroblasts, monocytes, and lungs affected by smoking and IPF to show that ATP11A and DPP9 were likely causal genes in critically ill COVID-19 and IPF." (PMID 39040187, 2024). "In contrast, we found that in those individuals younger than 50 years, the CC genotype at DPP9 rs10406145 was associated with severe COVID-19." (PMID 38694517, 2024). "Analysis of haplotype frequencies revealed that the coexistence of GAG at CCL2, OAS1, and DPP9 variants, respectively, in the same individual increased the presence of the severe COVID-19 phenotype (OR=2.273, 95% CI: 1.271-4.068, P=0.005305)." (PMID 38694517, 2024). "In contrast, the CC genotype at DPP9 rs10406145 was associated with severe COVID-19 in individuals younger than 50 years in an adjusted dominant model (interaction P value=0.021, OR=7.67, 95% CI 2.75-21.42)." (PMID 38694517, 2024). "Several studies have already pointed to rs12610495 DPP9 as a risk polymorphic variant for severe COVID-19." (PMID 39175753, 2024). "On the other hand, a significant association between the GG genotype of the DPP9 rs10406145 gene variant and the severe form of COVID-19 was found in males in an adjusted recessive genetic model (OR = 4.47, 95% CI 1.04-19.21)." (PMID 38694517, 2024). "Conversely, further genes linked to IPF such as dipeptidyl peptidase 9 (DPP9) have been independently reported to be associated with severe COVID-19." (PMID 37759460, 2023). "Genome-wide association studies (GWAS) have described polymorphisms in other COVID-19 candidate genes, such as DPP9 and TYK2, which have increased prevalence in COVID-19 patients." (PMID 36672770, 2022). "For variant rs2277735:A>G of DPP9, we also identified a significant association of the AG genotype with COVID-19 clinical variability, in which the AG genotype predisposes patients to moderate or severe/fatal cases." (PMID 36292769, 2022).
COVID-19 (continued). "The SNP rs2109069 within dipeptidyl peptidase 9 (DPP9) gene showed a significant association with COVID-19 severity in the Huoshenshan cohort (P = 0.032, OR = 1.33 for A allele)." (PMID 34465742, 2021). "Considering the evidence together, it is possible that decreased DPP9 expression in the lungs can predispose patients with COVID-19 to develop lung injury mediated by increased NLRP1-dependent pyroptosis." (PMID 34027315, 2021). "Colocalization of disease GWAS and eQTL signals indicates that decreased DPP9 expression is associated with increased risk of COVID-19 and IPF and that fibroblasts may drive the association at least in IPF lung." (PMID 39040187, 2024). "Furthermore, our study showed that rs12610495 DPP9 (risk allele G) is associated with a higher risk of severe COVID-19 in patients with obesity and also affects BMI in patients with severe COVID-19." (PMID 39175753, 2024). "Other genes commonly implicated in coronavirus disease 2019 include ACE2, IL6, DPP9, TYK2, TMPRSS2, FOXP4, and TNF, while the emerging genes consist of FURIN, CXCL10, OAS1, OAS2, OAS3, and ISG15." (PMID 35454970, 2022). "Using WES data, we focused on nine genes that have been reported to be involved in the SARS-CoV-2 entry pathway (ACE2, RAB7B, ADAM17, TMPRSS2), host immune response (IFNAR2, TYK2), and/or were previously shown to be associated with COVID-19 outcomes (DPP9, LZTFL1, SLC6A20)." (PMID 36292769, 2022). "Interestingly, we also find an inverse causal relation, namely, a predisposition for severe COVID-19 implying a predisposition for calciumconcentration, mediated by the gene DPP9." (PMID 36156592, 2022). "Additionally, genome-wide association studies have identified multiple genetic signals associated with severe COVID-19, including a variant within the DPP9 gene related to increased idiopathic pulmonary fibrosis risk." (PMID 36530872, 2022). "Combined with our human genetic data, these findings suggest that insufficient induction of DPP9 expression could predispose to severe COVID-19." (PMID 34001247, 2021). "Alternatively, the “G” allele could lead to lower DPP9 to increase inflammasome activation in lung tissue, a model consistent with “G” increasing risk of severe COVID-19 and this allele also increasing risk of idiopathic pulmonary fibrosis." (PMID 34001247, 2021). "Concordant with this hypothesis, the lead SNP rs12610495 is associated not only with decreased expression of DPP9 specifically in the lung and in macrophages but also with increased risk of severe COVID-19 with respiratory failure." (PMID 34027315, 2021). "The shared underlying genetic risk factors for IPF and COVID-19 suggest that DPP9 may have a common role in pathogenesis in these diseases." (PMID 34001247, 2021). "In terms of immunity, expression changes in CD151, PIDD1, and DPP9—genes involved in immune cell activation and NF-kB-mediated immune response —were associated with two distinct COVID-19 hg-replicated SNPs (rs3934992, rs12610495)." (PMID 34027315, 2021). "However, the presence of the DPP9 rs10406145-GG genotype showed a fourfold greater association with the severe form of COVID-19 in males than in females in a recessive genetic model (OR = 4.47, 95% CI 1.04-19.21), after adjustment for other confounding variables." (PMID 38694517, 2024). "Based on these data and the known biology, we developed alternative hypotheses for how this SNP might be regulating risk of severe COVID-19: DPP9 may be acting as a previously unrecognized receptor for SARS-CoV-2 or it may be inhibiting inflammation during COVID-19 infection." (PMID 34001247, 2021). "Less DPP9 would be expected to exacerbate inflammation in COVID-19, but in situ data suggests otherwise, whereby DPP9 overexpression in peripheral blood has been associated with increased COVID-19 severity." (PMID 40293537, 2025).
COVID-19 (continued). "The present study focused on the association between the SNVs CCL2 rs1024611, OAS1 rs10774671, and DPP9 rs10406145 and severe COVID-19 in a population from Quito, Ecuador." (PMID 38694517, 2024). "Genotyping for gene variants at rs1024611 (A>G), rs10774671 (A>G), and rs10406145 (G>C) of CCL2, OAS1, and DPP9 genes was performed on 100 COVID-19 patients (43 with severe form and 57 asymptomatic-mild) using RFLP-PCR." (PMID 38694517, 2024). "Our results showed that the severe COVID-19 phenotype was associated with the co-occurrence of the CCL2 rs1024611-G, OAS1 rs1024611-A, and DPP9 rs10406145-G alleles." (PMID 38694517, 2024). "Using age-based stratification analysis in adjusted genetic models, the interaction of CCL2, OAS1, and DPP9 SNVs with the presence of the severe COVID-19 phenotype was examined." (PMID 38694517, 2024). "Rs2277732 (DPP9), rs13081151 (FLT1P1), and rs11085727 (TYK2), among others, were considered significantly associated3with OA-COVID-19 hospitalization combined trait." (PMID 37398645, 2023). "Our MR analysis showed that the increased excision of intron junction chr19:4,814,337–4,717,615 in the DPP9 gene, which is preferentially spliced in ENST00000599248, was associated with reduced risk of COVID-19 severity." (PMID 37794074, 2023). "In a subset of 79 children, a genetic analysis was carried out to evaluate the role of common COVID-19 genetic risk factors (chromosome 3 cluster; ABO-blood group system; FUT2, IFNAR2, OAS1/2/3, and DPP9 loci)." (PMID 36873632, 2023). "Further research on the mechanism of action of DPP9 will contribute to the potential prevention and treatment of COVID-19." (PMID 36172198, 2022). "Collectively, our association analyses highlighted six common variants identified in previous GWAS or by the HGI—in/near LZTFL1, MHC, DPP9, IFNAR2, RPL24 and FOXP4—that are associated with COVID-19 as well as disease severity among cases." (PMID 35241825, 2022). "Five essential genes (IFNAR2, TYK2, OAS1, DPP9, and CCR2) have been linked to the most severe forms of COVID-19 disease, suggesting possible drug targets and vaccine epitopes." (PMID 35454970, 2022). "The COVID-19 Host Genetics Initiative (HG1) report concurred with the association of variants in ABO, SLC6A20, TYK2, DPP9, IFNAR2, and additionally reported a variant in Protein Phosphatase 1 Regulatory Subunit 15A (PPP1R15A) in influencing COVID-19 severity." (PMID 36143338, 2022). "Considering the role of DPP9 as an inflammasome inhibitor, these observations assumed homeostasis responded to the deleterious inflammation in more severe cases of COVID-19." (PMID 36292769, 2022). "DPP9 expression was remarkably increased in the peripheral blood of moderate/severe COVID-19 patients compared with healthy controls." (PMID 36292769, 2022). "In this work, we detected the clinical significance of IFNAR2 (2 SNPs), SLC6A20 (1 SNP) with respect to COVID-19 susceptibility and ADAM17 (2 SNPs), TMPRSS2 (1 SNP), TYK2 (1 SNP), DPP9 (1 SNP) with respect to the severity of the disease." (PMID 36292769, 2022). "Intronic SNPs rs12610495 and rs2109069 in DPP9 are genome-wide significant loci for severe COVID-19, idiopathic pulmonary fibrosis and idiopathic interstitial pneumonia." (PMID 33915844, 2021). "Our studies of COVID-19 provide a test case for this and revealed possible mechanisms underlying the associations of severe COVID-19 with ABO and DPP9." (PMID 34001247, 2021). "Transcriptomics from peripheral blood of COVID-19 patients demonstrated that DPP9 was induced in SARS-CoV-2 compared to healthy controls or those with bacterial infection." (PMID 34001247, 2021). "DPP9 levels were significantly increased in COVID-19 patients compared to the other groups (fold-change = 1.15, p = 0.003 adjusted by Benjamini-Hochberg method)." (PMID 34001247, 2021).
COVID-19 (continued). "Comparing COVID-19 data vs. each comparator individually revealed that DPP9 levels were elevated vs. healthy controls (p = 0.0016) and bacterial infection (p = 0.0078) but not influenza or other coronavirus infection." (PMID 34001247, 2021). "Levels of DPP9 expression across 46 COVID-19 patients were compared to individuals with seasonal coronavirus, influenza, bacterial pneumonia, and healthy controls." (PMID 34001247, 2021). "An association study based on ~50,000 COVID-19 patients further supported the association of genetic variants in ABO, TYK2, DPP9, IFNAR2, SLC6A20 and Protein Phosphatase 1 Regulatory Subunit 15A (PPP1R15A) with the severity of COVID-19." (PMID 34575070, 2021). "To further examine the role of DPP9 in COVID-19, we analyzed previously generated transcriptomics of peripheral blood from COVID-19 patients." (PMID 34001247, 2021). "Application of iCPAGdb to a recent GWAS of severe COVID-19 demonstrated unexpected overlap of GWAS signals between COVID-19 and human diseases, including with idiopathic pulmonary fibrosis driven by the DPP9 locus." (PMID 34001247, 2021). "While DPP9 and TYK2 are thought to be associated with host-driven inflammatory lung injury linked to life-threatening COVID-19, IFNAR2 and OAS genes have been associated with innate antiviral defences." (PMID 34575070, 2021). "When adding the naïve controls (n = 954; Methods section), the rs2109069 in DPP9 gene and rs657152 in ABO gene were significantly associated with COVID-19 severity (for rs2109069 A allele: P = 0.0042, OR = 1.33; for rs657152 A allele: P = 0.0017, OR = 1.27)." (PMID 34465742, 2021). "Although the mechanism of these SNPs has not been investigated, it is widely speculated that these SNPs produce less DPP9 than wild-type alleles and consequently lead to more NLRP1 activation and aggravation of inflammation in COVID-19." (PMID 40293537, 2025). "Other Neanderthal-related haplotypes reported to correlate with the severity of COVID-19 include genetic elements coding for the DPP9 protein (chr19, p13.3 –lead SNP: rs2109069) and the interferon alpha receptor (IFNAR2) protein (coding chr21, q22.1 –lead SNP: rs2236757)." (PMID 39752416, 2025). "Furthermore, human DPP9 gene expression in peripheral blood cells increases during moderate and severe COVID-19." (PMID 40293537, 2025). "We previously reported that based on transcriptomics from patients infected with COVID-19 that DPP9 decreased concordantly with resolution of infection, and therefore, may be dampening the inflammatory response." (PMID 39876559, 2025). "During COVID-19, we found that DPP9 was significantly decreased in AT1s and AT2s." (PMID 39040187, 2024). "We also found lower DPP9 expression (and higher methylation at a specific CpG) from the G allele of rs12610495, acting in fibroblasts and in IPF lungs, and increased risk of IPF and critically ill COVID-19." (PMID 39040187, 2024). "However, we showed that the DPP9 rs10406145-GG genotype was more common in the asymptomatic-mild group compared to individuals with the severe COVID-19 phenotype." (PMID 38694517, 2024). "No allele or genotype of the OAS1 or DPP9 loci was significantly associated with the severe COVID-19 phenotype." (PMID 38694517, 2024). "By conducting SMR and HEIDI methods, several non-MHC region SNPs were identified as common shared genetic loci including rs143334143 (TCF19), rs2277732 (DPP9), rs77534576 (DLX3), and rs13081151 (FLT1P1), among others, which were significantly associated with OA-critical COVID-19 combined trait." (PMID 37398645, 2023). "Both rs2834161 and rs12610495 (DPP9) showed strong but no statistically significant tendencies for association with severe COVID-19 in younger people." (PMID 38003785, 2023).